AGTR2 (angiotensin II receptor type 2)
Diseases named in the same sentence as AGTR2 in open-access papers (continued):
Sharing a sentence is not in itself a finding about the gene and the disease.
pulmonary hypertension (3 papers, 2018 to 2023). Increased pressure within the pulmonary circulation due to lung or heart disorder. "Apelin (APLN), angiotensin I converting enzyme 2 (ACE2) and angiotensin II receptor type 2 (ATGR2) cause vasodilatation and normally inhibit the development of pulmonary hypertension and in each case reductions of protein expression have been shown to contribute to the development of disease." (PMID 34068984, 2021).
rheumatoid arthritis (3 papers, 2017 to 2022). A chronic, systemic autoimmune disorder characterized by inflammation in the synovial membranes and articular surfaces. "Oral administration of losartan has also been shown to have beneficial effects in the musculoskeletal system such as in rheumatoid arthritis (RA) via up-regulation of angiotensin II receptor type 2 (AGT2R) and down-regulation of angiotensin II receptor type 1 (AGTR1)." (PMID 35372645, 2022). "Notably, it was reported that AGTR1 expression was detected not only in articular chondrocytes derived from OA and rheumatoid arthritis (RA) patients but also in normal chondrocytes, whereas AGTR2 expression was detected in diseased chondrocytes only." (PMID 34502113, 2021).
lung disease (2 papers, 2015 to 2019). "Given sub-optimal content of epithelia in the GTEx lung tissue samples by design, we calculated SLC6A14 eQTLs from the CF nasal epithelia which provided colocalization evidence with the lung disease associated variants(p = 2.4x10-4); AGTR2 was not expressed in the nasal epithelia." (PMID 30807572, 2019). "The chrX locus contains AGTR2 and SLC6A14 and either gene, or possibly both, could modify lung disease." (PMID 26417704, 2015).
male infertility (2 papers, 2018 to 2022). The inability of the male to effect fertilization of an ovum after a specified period of unprotected intercourse. "Therefore, a specific agonist of AGTR2 should be considered for the development of therapeutic methods to treat male infertility caused by impaired ADGRG2-Gq-CFTR signaling, such as that observed in CF patients." (PMID 29393851, 2018).
melanoma (2 papers, 2021 to 2024). A malignant, usually aggressive tumor composed of atypical, neoplastic melanocytes. "Similarly, in human melanoma cell lines, blockade of the angiotensin II receptor type 2 results in the inhibition of cell growth and angiogenesis." (PMID 38922022, 2024). "With regards to AT2R, Ang II treatment promotes cell proliferation in AGTR1 gene-lacking melanoma cells but not in AGTR1 and AGTR2 genes lacking melanoma cells, which proves the Ang II-dependent proliferative effect of AT2R." (PMID 34539580, 2021).
metabolic syndrome (2 papers, 2012 to 2022). A cluster of metabolic risk factors for CARDIOVASCULAR DISEASES and TYPE 2 DIABETES MELLITUS. "The reduced expression of Agtr2 in IUGR-R animals relative to macrosomic animals is also interesting since it is thought that an overactive renin-angiotensin system (RAS) is involved in metabolic syndrome." (PMID 35208177, 2022).
systemic sclerosis (2 papers, 2023 to 2025). A chronic disorder, possibly autoimmune, marked by excessive production of collagen which results in hardening and thickening of body tissues. "Highly significant DEGs including CYP1A1 and AGTR2 might be associated with systemic sclerosis." (PMID 38137330, 2023).
X-linked intellectual disability (2 papers, 2012 to 2023). An X-linked intellectual deficiency in which not enough information is known, reported or published to indicate whether a gene causes non-syndromic or syndromic presentations. "Mutations in the AGTR2 gene correlate with the development of human X-linked intellectual disability." (PMID 23320146, 2012). "Notably, mutations of AGTR2 were associated with X-linked intellectual disability (XLID)." (PMID 37511534, 2023).
autism (1 paper, 2019). Persistent deficits in social interaction and communication and interaction as well as a markedly restricted repertoire of activity and interest as well as repetitive patterns of behavior. "Genetic variants in AGTR2 observed in prematurity have also been identified in human X-linked intellectual disability, with clinical features including seizures and autistic behavior and syndromic autism and could significantly disrupt the developing MGVHB axis at several levels." (PMID 30109601, 2019). "We predict that the AGTR2 variants involved in the brain maturation and oxytocin-arginine-vasopressin (OXT-AVP) pathways, related to social behavior, will contribute to our understanding of the link between prematurity and autism paving a way to new therapies." (PMID 30109601, 2019). "We tentatively predict that AGTR2 gene variants and their effects on the OXT-AVP pathways involved in major physiological processes, learning, and social behavior may contribute to further understanding of the link between prematurity and autism." (PMID 30109601, 2019).
colorectal cancer (1 paper, 2021). A primary or metastatic malignant neoplasm that affects the colon or rectum. "AGTR2 was a risk factor in follicular lymphoma and colorectal cancer, whereas MAS1 was a protective factor in most tumors." (PMID 34671200, 2021).
cystic fibrosis (1 paper, 2022). Autosomal recessive disorder caused by pathogenic variants in the CFTR gene (cystic fibrosis transmembrane conductance regulator), which encodes a chloride and bicarbonate channel expressed in epithelial cells, and follow the diagnosis criteria. "Those two patients presented ultra-rare variants in ACE2 gene, likely responsible for reduced viral load, and in AGTR2 gene, which reduced activity is known to prevent cystic fibrosis pulmonary manifestation." (PMID 34889978, 2022).
glioblastoma (1 paper, 2024). The most malignant astrocytic tumor (WHO grade IV). "The combined expression of RAS receptors (ATP6AP2, AGTR1, and AGTR2) was positively associated with gene pathways involved in hypoxia, microvasculature, stem cell plasticity, and the molecular characterisation of glioblastoma subtypes." (PMID 38607073, 2024). "We, thus, examined the relationship of RAS receptors (ATP6AP2, AGTR1, and AGTR2) with TME expression within TCGA glioblastoma samples." (PMID 38607073, 2024). "The majority of genes (ATP6AP2, AGTR1, ACE, and AGT) were consistently expressed in glioblastoma cases, with the exception of AGTR2 and REN." (PMID 38607073, 2024). "The baseline mRNA expression of RAS genes (ATP6AP2, AGTR1, AGTR2, AGT, ACE, and REN) were explored in 12 patient-derived glioblastoma cell lines." (PMID 38607073, 2024). "The expression of RAS receptors (AGTR1, AGTR2, and ATP6AP2) has been demonstrated on the glioblastoma microvasculature, and the inhibition of AGTR1 or AGTR2 reduced glioblastoma cell growth in vitro and in vivo." (PMID 38607073, 2024). "The combination of TMZ + RT resulted in a slight but significant increase in the expression of ATP6AP2, AGTR1, and ACE, while AGT and the lowly expressed AGTR2 and REN remained unchanged across all 12 glioblastoma cell lines." (PMID 38607073, 2024). "We studied the expression of RAS-related genes (ATP6AP2, AGTR1, AGTR2, ACE, AGT, and REN) in The Cancer Genome Atlas (TCGA) glioblastoma cohort, their relationship to patient survival, and association with tumour microenvironment pathways." (PMID 38607073, 2024). "Although this study did not explore the targeting of RAS components, inhibition of RAS receptors such as AGTR1, AGTR2, and ATP6AP2 have been demonstrated to reduce glioblastoma cell growth, proliferation, and/or angiogenesis." (PMID 38607073, 2024). "ATP6AP2, AGTR1, AGTR2, AGT, and ACE had low frequencies of CNAs (<1%) in glioblastomas; however, REN was altered in 6% of glioblastoma cases." (PMID 38607073, 2024). "In cases of glioblastoma within the TCGA, ATP6AP2, AGTR1, ACE, and AGT had consistent expressions across samples, while AGTR2 and REN were lowly expressed." (PMID 38607073, 2024). "As ATP6AP2, AGTR1, and AGTR2 are the main receptors in the RAS; this suggests that glioblastomas have a greater capacity to utilise this pathway for their survival." (PMID 38607073, 2024). "Here, we investigated the gene expression of RAS components (ATP6AP2, AGTR1, AGTR2, ACE, AGT, and REN) in glioblastoma patient samples from The Cancer Genome Atlas (TCGA) and their association with survival outcomes and the expression of TME pathways." (PMID 38607073, 2024). "The majority of RAS genes (ATP6AP2, AGTR1, AGTR2, and ACE) in our study were highly expressed in glioblastomas compared to LGGs." (PMID 38607073, 2024). "Progression-free survival (PFS) and overall survival (OS) were compared across TCGA glioblastoma cases, stratified from high and low expression of ATP6AP2, AGTR1, AGTR2, ACE, AGT, and REN genes." (PMID 38607073, 2024). "The level of expression of ATP6AP2, AGTR1, AGTR2, and ACE genes in glioblastomas was similar to that observed in a range of other solid tumours and haematological cancers." (PMID 38607073, 2024). "Baseline expressions of RAS genes were relatively similar to the TCGA glioblastoma cohort, where REN and AGTR2 were very lowly expressed while ATP6AP2, AGTR1, ACE, and AGT were consistently expressed." (PMID 38607073, 2024). "Although AGTR2 was significantly higher in glioblastomas compared to LGG cases, this gene was not expressed in most glioblastoma cases." (PMID 38607073, 2024). "Furthermore, inhibition of AGTR2 using a derivative of EMA401, a preclinical drug investigated for peripheral neuropathic pain, reduced glioblastoma cell growth in vitro and in an intracranial mouse model." (PMID 38607073, 2024). "The majority of glioblastoma cases expressed ATP6AP2, AGTR1, ACE, and AGT but not AGTR2 and REN." (PMID 38607073, 2024).
Hyperglycemia (1 paper, 2018). An increased concentration of glucose in the blood. "On this note, it has been reported that AGTR2 nuclear transport, promoted by hyperglycemia, also increases intracellular A-II." (PMID 30564297, 2018).
hypothyroidism (1 paper, 2025). Abnormally low levels of thyroid hormone. "Fetal hypothyroidism was found to have temporal and tissue‐specific effects on the expression of many RAS genes including AGT, ACE, ACE2, AGTR1, and AGTR2." (PMID 40939099, 2025).
kidney injury (1 paper, 2023). Trauma to the kidney. "The highly abundant angiotensin II receptor protein expressed in rat fetus is AT2R indicating that Agtr2 is part of fetal gene program and knocking out Agtr2 increases high fat diet-induced kidney injury." (PMID 36909327, 2023).
leukemia (1 paper, 2025). A malignant (clonal) hematologic disorder, involving hematopoietic stem cells and characterized by the presence of primitive or atypical myeloid or lymphoid cells in the bone marrow and the blood. "This unbiased computational approach identified AGTR2 (encoding AT2R) as a key regulator of leukemia biology." (PMID 41497603, 2025). "Our data add a new dimension by showing a 3D genome wiring change as a driver of AGTR2 silencing – a strategy that leukemia cells appear to use to lock away a gene that is deleterious to their maintenance." (PMID 41497603, 2025). "The epigenetic plasticity of the AGTR2 locus also underscores how dynamic the leukemia genome is in sculpting its regulatory landscape to favor malignancy." (PMID 41497603, 2025). "Unlike many genetic drivers of leukemia, we found no recurrent mutations in AGTR2 in large AML cohorts, implying no positive selection for coding alterations." (PMID 41497603, 2025).
Lewis lung carcinoma (1 paper, 2020). "The complex of dTAT- AGTR2-Ca2 + could inhibit the growth of Lewis lung carcinoma in mice." (PMID 32699529, 2020).
metabolic syndrome X (1 paper, 2022). "For example, in the subnetwork for metabolic syndrome X, pathogenesis genes AGTR2 and ADRA1A are at the top hierarchical layer for chemokine signaling, while IRF1, MXZB1, MTTP, and CNTC are at the top layer in cytokine signaling." (PMID 35404985, 2022).
oral squamous cell carcinoma (1 paper, 2018). "Here, we investigated the role of RAS, and specifically that of AGTR2, in oral squamous cell carcinoma (OSCC) progression." (PMID 30564297, 2018).
pheochromocytoma (1 paper, 2012). "These receptors belong to the G protein-coupled receptor family, and the presence of AGTR1 and AGTR2 in the plasma membrane of rat pheochromocytoma cells, rat kidney and many others has been well documented." (PMID 23781300, 2012).
schizophrenia (1 paper, 2023). A major psychotic disorder characterized by abnormalities in the perception or expression of reality. "Thus, we suggest that schizophrenia might be one of the clinical phenotypes of AGTR2 mutations." (PMID 37511534, 2023). "In family 1, with singleton schizophrenia, we detected four rare variants in genes implicated in schizophrenia, including p.Arg1627Trp of LAMA2, p.Pro1338Ser of CSMD1, p.Arg691Gly of TLR4, and Arg182X of AGTR2." (PMID 37511534, 2023).
viral disease (1 paper, 2025). "In contrast, triterpenoid-type compounds (e.g., GPM24, GPM30, GPM32) interacted with a separate subset of targets including ACE, AGTR2, VDR, and were more involved in cardiovascular and renin–angiotensin system-related pathways, as well as metabolic and viral disease modules." (PMID 41471341, 2025).
Zika virus infection (1 paper, 2016). "The novel interactions of FNDC3B with IFITM3 and SPTA1, ARPC1B and AGTR2 with IFITM1 may shed light on mechanisms of host invasion underlying cytoskeletal re-arrangements that follow Zika virus infection." (PMID 29333229, 2016).
tumor (24 papers, 2010 to 2025). "Another member of the RAS pathway, the angiotensin II receptor type 1 (AGTR1) was also associated with metastatic PCa cells, while the angiotensin II receptor type 2 inhibits tumor growth, induces apoptosis, and reduces Ki‐67 and AR expression." (PMID 36329628, 2023). "For example, evidence indicates that angiotensin II receptor type-1 (AT1R) blockade with an ARB, which results in unopposed angiotensin II receptor type-2 (AT2R) stimulation is capable of causing tumor angiogenesis in vivo." (PMID 35235571, 2022). "Nuclear AGTR2 positivity was associated with tumor expansion, nodal metastasis and clinical stage." (PMID 30564297, 2018). "Conversely, AGTR2 can exert anti-tumor effects predominantly through its antagonistic action on angiogenesis." (PMID 40099255, 2025). "While the observed differences lack statistical significance, we observed a gradual reduction in the expression of both AQP1 and AGTR2 as tumor progression advanced." (PMID 37991139, 2023). "MIA tumor cells exhibit high expression of aquaporin‐1 and angiotensin II receptor type 2 and a basal‐like molecular character." (PMID 37991139, 2023). "MIA tumor cells exhibited high expression of aquaporin‐1 and angiotensin II receptor type 2 and a basal‐like molecular character." (PMID 37991139, 2023). "It has been shown that the perfusion of tumor vessels is gradually shifted from poor to good after slow systemic administration of AGTR2." (PMID 33672813, 2021). "In tumor tissue, AGTR2 and MAS1 were weakly expressed; in contrast, ACE and AGT presented broad expression across 33 cancer types." (PMID 34671200, 2021). "In most tumors, ACE and AGTR1 (in the classical axis) possessed a closer correlation with non-tumor components than those members in the alternative axis and AGTR2." (PMID 34671200, 2021). "Suppressing AGTR2 is efficient to inhibit tumor growth time and dose dependently by arresting tumor proliferation, promoting tumor apoptosis, and inhibiting tumor angiogenesis." (PMID 33133165, 2020). "By day 7, IFNγ, CSF2, CXCL10, GZMB, PTGS2, TNFα, CD80, CCL22, IL12a, IL13, IL1b, IL6, NOS2, and CTLA4 were significantly upregulated in the tumor-bearing mice bladders and AGTR2 and GATA3 were downregulated." (PMID 22013484, 2011). "It has been reported that tumor vessels are insensitive to angiotensin receptor type 2 (AGTR2)." (PMID 33672813, 2021). "As integral parts of the RAS, angiotensin II receptors, including angiotensin II receptor type 1 (AT1R) and angiotensin II receptor type 2 (AT2R) are implicated in tumor angiogenesis and tumor metastasis by modulating vascular wall thickness, vascular injury, and cytokine secretion." (PMID 34831211, 2021). "Notably, losartan, an angiotensin receptor blocker, inhibited intracellular angiotensin-II production and AGTR2 nuclear localization to enhance the antitumoral effect of 5-FU in an OSCC tumor model." (PMID 30564297, 2018). "AGTR2 was consistently downregulated in all tumor bearing samples." (PMID 22013484, 2011). "To validate the tumor suppressor role of AT2R, we developed murine AML models driven by MLL-AF9 or AML1-ETO9a fusions with either Agtr2 knockdown or enforced expression." (PMID 41497603, 2025). "AGTR2 was positively related with JUN, a common transcription factor promoting tumor proliferation in both adrenocortical carcinoma (ACC; Cor = 0.614) and TGCT (Cor = 0.589)." (PMID 34671200, 2021). "MIA tumor cells exhibited high expression of AQP1 and AGTR2 and a basal‐like molecular character." (PMID 37991139, 2023). "AGTR2 and MAS1 were weakly expressed in normal and tumor tissues as well as cancer cell lines." (PMID 34671200, 2021).
cancer (17 papers, 2006 to 2025). A tumor composed of atypical neoplastic, often pleomorphic cells that invade other tissues. "RAS encompasses multiple axes, among which the AngII signaling through its receptors AGTR1 and AGTR2 has been the subject of extensive research, where this axis is known to intersect with a variety of pathways implicated in tumorigenesis, highlighting its potential role in cancer biology." (PMID 40099255, 2025). "Angiotensin-II (A-II) type 2 receptor (AGTR2) seems to be involved in different types of cancer; its role, however, is still unclear." (PMID 30564297, 2018). "AGTR2 immunoreactivity was detected in the nuclei of cancer and stromal cells." (PMID 30564297, 2018). "In this study, we comprehensively integrated and analyzed the molecular characteristics of 6 significant members of the RAS family across pan-cancer: AGT, ACE, ACE2, AGTR1, AGTR2, and MAS1." (PMID 34671200, 2021). "The oncoprint displayed an overall alteration frequency of RAS family of 15.2% in TCGA pan-cancer across TCGA cancers, with the highest frequency existing for ACE (4%), followed by AGT (3%), AGTR1 (3%), ACE2 (2.3%), AGTR2 (1.5%) and MAS1 (1.4%)." (PMID 34671200, 2021). "From the RAS pathway, possible receptors are AGTR2 and MAS1 that have opposing effects to that of AGTR1 in several cancers." (PMID 30845964, 2019).
cardiovascular diseases (6 papers, 2017 to 2026). "It is unknown whether miRNAs bind to angiotensin II (Ang II) type 2 receptor (AGTR2), a critical protective GPCR in cardiovascular diseases, as ligands or intracellular interactomes." (PMID 35637969, 2022).
infection (4 papers, 2013 to 2023). The state of being infected such as from the introduction of a foreign agent such as serum, vaccine, antigenic substance or organism. "Therefore, an increased expression of AGTR2+ cells in gut tissues during infection may promote increased susceptibility to SARS-CoV-2 infection." (PMID 35281029, 2022). "In contrast, compared to pre infection (0.00016 ± 0.00005, p = 0.002) and acute infection (0.0003 ± 0.00008, p = 0.01), AGTR2 transcripts were significantly increased during chronic infection (0.0014 ± 0.0004) by 8.8 and 4.7-fold, respectively." (PMID 35281029, 2022). "A significant increase in AGTR2+ cells was detected during chronic (mean ± SE: 632 ± 90, p = 0.015) compared to pre infection (395 ± 69)." (PMID 35281029, 2022). "Protein expression profiling also revealed significant upregulation of AGTR2 after infection." (PMID 35281029, 2022). "All virus isolates induced the mRNA expression of ACE2 and AGTR2, the receptor of ACE2, in the lungs upon infection, with the highest levels on 1 and 3 dpi followed by a drop to background levels by 5 dpi." (PMID 36992320, 2023).